CRP (C-reactive protein)
Diseases named in the same sentence as CRP in open-access papers (continued):
Sharing a sentence is not in itself a finding about the gene and the disease.
cancer (continued). "Expected, combination of CRP, ARHGEF 11 and CA125 improved the predictive performance with an AUC value of 0.98 (sensitivity=0.94, specificity=0.97, Cancer correct prediction rate=16/17, Non-cancer correct prediction rate=29/30)." (PMID 33613752, 2021). "Combination of CRP, ARHGEF 11 and CA125 improved the predictability of CA125 alone in the distinguishment of cancer from non-cancer patients significantly, especially improved the specificity, which improved the deficiency of CA125 in the disease diagnosis." (PMID 33613752, 2021). "Age, body mass index, C-reactive protein, cholesterol and ASM residual enzymatic activity were not correlated with cancer occurrence." (PMID 34768550, 2021). "It is not surprising to detect increased levels of CRP, NLR, or GPS in cancer because of the importance of the inflammation in the development of cancer." (PMID 34720749, 2021). "Exercise plays a role in mediating the effects of chronic inflammation, reducing inflammatory markers such as C-reactive protein (CRP), tumor necrosis factor alpha, and various types of interleukin (IL), including IL6, in people with and without cancer." (PMID 31013573, 2019). "Basic biomarkers such as haemoglobin, leukocytes, thrombocytes, CRP and LDH have proven to have prognostic value in many cancers, whereas their predictive values have not yet been examined in the NSSC-CPP setting." (PMID 29197366, 2017). "This study reported significant differences in the ranges of CRP, TK1, and NI between dogs without cancer and those that developed cancer." (PMID 27747218, 2016). "Compared to control group, higher plasma levels of CRP, fibrinogen, IL-6, TNF-α, IL-1β, MMP-9, VEGF, TF antigen, and sP-selectin were observed in cancer patients with and without DVT (P<0.01)." (PMID 26192925, 2015). "C-reactive protein (CRP), a non-specific marker of systemic inflammation, has been identified as a predictor of poor prognosis in patients with various cancers." (PMID 25612215, 2015). "In summary, while CRP is a valuable marker for inflammation, its nonspecific nature necessitates the inclusion of additional biomarkers, such as TK1, to improve the accuracy of early cancer detection." (PMID 40351765, 2025). "The implementation of a KD intervention in cancer patients did not result in significant changes in the following nine indicators: HDL cholesterol, triglycerides, CRP, IGF-1, TNF-α, creatinine, urea, energy intake, and age at the time of the dietary intervention." (PMID 40756563, 2025). "When IPR was compared with CRP, the total NRI was 0.91 (p < 0.001), mainly driven by a large NRI− of 0.66, reflecting substantial improvement in the correct classification of patients without cancer." (PMID 40362613, 2025). "Cancer patients have chronically increased Interleukin-6 (IL-6) in the circulating blood, affecting the acute-phase proteins (APPs); positive APP corresponds to CRP, and negative APP to albumin." (PMID 35204642, 2022). "Six variables were selected in the scoring model: Age ≤ 46 years old (4.96 points), Male (2.44 points), No cancer (3.19 points), Positive T-cell Spot (T-SPOT) results (4.69 points), Adenosine Deaminase (ADA) ≥ 24.5U/L (2.48 point), C-reactive Protein (CRP) ≥ 52.8 mg/L (1.84 points)." (PMID 36056429, 2022). "Although several noninfectious conditions (trauma, surgery, and carcinoma) could also increase PCT levels, PCT still has better accuracy in differentiating bacterial infections than CRP, WBC, and NLR." (PMID 36443747, 2022). "We also identify factors associated with low response (last quartile; IgG<500AU/mL): immunocompromised status, age, absence of RAAS inhibitors, low lymphocytes count, high C Reactive Protein; and with high response (high quartile; IgG>7000AU/mL): age; previous SARS-CoV-2 infection and active Cancer." (PMID 34610031, 2021).
cancer (continued). "Patients with cancer having COPD have worse survival than those without COPD because COPD increases C-reactive protein levels, a biomarker of systemic inflammation, which is associated with an increased risk of cancer mortality, including for extrapulmonary cancers." (PMID 34683099, 2021). "There appears to be emerging evidence for primary thromboprophylaxis, based on risk assessment with biomarker screening including P-selectin, CRP, factor VIII, prothrombin F 1 + 2, and TF-bearing microparticle levels in patients with cancer, but these are not yet validated." (PMID 31741612, 2019). "Although both pretreatment CRP and ALB can be the independent prognostic factors of cancer patients, they are not perfect predictors because they can be easily influenced by some nontumor-related factors, such as diet, overhydration, and inflammation outside the tumor site." (PMID 29568406, 2018). "C-reactive protein (CRP) testing was also not ordered in either case and is not routinely ordered in our clinic for CIC due to the nonspecific nature of elevated CRP values in advanced cancer patients, many of whom have chronic, systemic inflammation from their underlying malignant disease." (PMID 41036260, 2025). "However, it did indicate that a combination of CRP, IL‐6, YKL‐40, CEA and CA 19‐9 can identify a subgroup of patients with nonspecific signs and symptoms of cancer who will develop cancer, and that they have a very poor prognosis if all biomarkers are elevated." (PMID 36440611, 2023). "Apart from weight loss and fatigue, cachectic patients often clinically present with high levels of C reactive protein (CRP) and low levels of albumin as a consequence of inflammation, but so far, specific biomarkers that could help the early detection of cancer cachexia are lacking." (PMID 36768173, 2023). "Finally, we did not observe a correlation between the levels of the inflammatory markers CRP or IL-6 and DELFI score in cancer-free individuals, consistent with the notion that cancer-specific fragmentation is not affected by the presence of acute or chronic inflammatory conditions." (PMID 34417454, 2021). "CRP is one of the most frequently used serum markers to assess cancer prognosis, but due to lack of specificity, several studies have been reported, including Glasgow Prognostic Score (Glasgow Prognostic Score (GPS) and CRP/albumin ratio (CAR), which combine CRP and albumin." (PMID 32676164, 2020). "While looking at all the well performed and published data available, proofing the role of CRP, albumin, GPS, mGPS, and C/A ratio as prognostic factor for many different cancers, we can only speculate why we could not find significance concerning OS and DFS in our collective." (PMID 28740506, 2017). "However, in this study in advanced cancer patients, we could not find evidence of a relationship between CYP2C19 activity and serum levels of cytokines or the acute phase response protein CRP." (PMID 18854824, 2008). "As on one hand, TIMP-1 has a growth factor-like role directly affecting cancer cell growth, invasion, and migration independent of TIMP:s inhibition of MMPs, and on the other hand, both MMPs and TIMP-1 play an important role in inflammatory processes, we explored whether MMPs and CRP correlate." (PMID 29929486, 2018).
cardiovascular disease (2,079 papers, 2004 to 2026). "Few CpGs appeared in several EWAS, for example, 100 CpGs were linked to both T2D incidence and CRP and 20 CpGs were associated with CRP, T2D incidence and cardiovascular disease." (PMID 41547928, 2026). "This variation aligns with previous MR studies investigating the impact of CRP on other health outcomes, such as cardiovascular disease and frailty, where causal estimates have similarly varied across different analytical approaches." (PMID 41172260, 2026). "Inflammation is widely recognised as a precursor to cardiovascular disease, with elevated levels of CRP associated with an increased risk of cardiovascular events." (PMID 41231203, 2026). "The severity of cardiovascular disease is linked to C-reactive protein, interleukin 6, and C-type natriuretic peptide levels, stressing the need for a sensitive sensor that can detect these biomarkers at ultralow levels in real time." (PMID 41752974, 2026). "Elevated CRP levels have been associated with adverse health outcomes such as cardiovascular disease, diabetes, and physical function decline, underscoring its relevance in understanding the mechanisms underlying balance impairments." (PMID 41172260, 2026). "Clinically, serum CRP concentrations are used to classify cardiovascular disease risk into low (<1 mg/L), intermediate (1–3 mg/L), and high (>3 mg/L)." (PMID 40949172, 2025). "Continuing with a well-established inflammatory biomarker, CRP, it should be noted that multiple other studies have already investigated the association between C-reactive protein and FC in non-cardiovascular disease." (PMID 40283065, 2025). "Risk factors such as chronic pulmonary and cardiovascular diseases and elevated C-reactive protein (CRP) and D-dimer levels have also been linked to poorer outcomes following COVID-19 infection." (PMID 40266073, 2025). "We also observed a reduction in ADMA post-intervention; elevated ADMA, an endogenous nitric oxide synthase inhibitor, is linked to cardiovascular diseases and interacts with CRP to influence cardiovascular events." (PMID 41403880, 2025). "Relevant meta-analysis data showed that elevated CRP levels can increase the risk of developing cardiovascular disease, leading to worsening cardiovascular events and affecting the prognosis of patients." (PMID 40779499, 2025). "C-reactive protein (CRP) is a molecule largely associated with inflammation and cardiovascular disease, and over the past few decades its consistently high concentration in plasma and sera in KT recipients has been described as a biomarker for renal rejection." (PMID 40566549, 2025). "Previous studies have shown that NLR and CRP, as key indicators of cardiovascular risk, can effectively enhance the risk stratification assessment of patients with various cardiovascular diseases." (PMID 41035697, 2025). "Meanwhile, CRP is the most widely studied of the inflammatory markers associated with cardiovascular diseases (CVDs), and has even been used as the “gold standard” for CVD risk assessment." (PMID 40104822, 2025). "CRP has been well established as a prognostic marker for cardiovascular disease and has been incorporated into many diagnostic and prognostic risk assessment models." (PMID 40278353, 2025). "The atherogenic index of plasma (AIP), an emerging biomarker of lipid dysregulation, and high-sensitivity C-reactive protein (hs-CRP), an established marker of inflammation, are both implicated in the development of cardiovascular disease (CVD)." (PMID 40842496, 2025). "Circulating CRP is increased in many inflammatory conditions and even a moderate elevation is associated with a higher risk of cardiovascular disease." (PMID 40943715, 2025). "CRP is a risk marker for future cardiovascular diseases (CVDs), and IL-6 and SAA are regarded as risk markers and even mediators for CVD." (PMID 40332485, 2025).
cardiovascular disease (continued). "CRP, an acute-phase protein, is a well-established marker of systemic inflammation and is associated with various chronic diseases, including cardiovascular disease (CVD) and metabolic disorders." (PMID 39980916, 2025). "This is confirmed by the marker hs-CRP (high sensitivity C-reactive protein; a factor measuring the risk of cardiovascular diseases), which increases in parallel with the increase in ACR level." (PMID 40989118, 2025). "Although CRP differences can influence CRP levels, this protein remains a valuable tool in the diagnostic panel used for evaluating cardiovascular diseases." (PMID 40725061, 2025). "A “portfolio diet,” which emphasizes foods known to reduce cardiovascular disease risk, has shown beneficial effects on C-reactive protein (CRP) and LDL cholesterol." (PMID 41227672, 2025). "MCR can be linked to poorer vascular health due to its association with physical frailty and slower walking speed, while high CRP serum levels are a known risk factor for cardiovascular diseases." (PMID 39913250, 2025). "A possible explanation lies in the fact that regular PA stimulates the release of myokines, which regulate inflammatory markers such as TNF-α, IL-6, IL-1β, and CRP, all of which are associated with cardiovascular disease." (PMID 40868631, 2025). "The reason for the lack of correlation for a given extract between anti-inflammatory effects on joints and levels of CRP, an acute phase reactant also associated with cardiovascular disease risk, is unclear." (PMID 40278395, 2025). "Elevated CRP levels have been linked to various adverse health outcomes, including cardiovascular disease and mortality." (PMID 39980916, 2025). "A high CRP level has been thought to indicate a proinflammatory state and to be a risk factor of cardiovascular disease." (PMID 40422877, 2025). "More precisely, cardiovascular disease and T2D have been linked to increased levels of circulating cytokines, especially interleukins and C-reactive protein." (PMID 40136627, 2025). "Prior studies have linked the risk of cardiovascular disease (CVD) to serum levels ofhs-CRP, a measure of systemic inflammation and an atherosclerotic mediator." (PMID 40978613, 2025). "For systemic risk assessment, elevated CRP levels, when combined with IL-6, serve as significant predictors of cardiovascular disease." (PMID 40418274, 2025). "This research shows that asthmatic patients who SNORING found to have high level of CRP raises cardiovascular disease risk." (PMID 40662069, 2025). "On the other hand, cardiovascular disease risk and prognosis are substantially correlated with C-reactive protein (CRP), one of the indicators of inflammation." (PMID 38349930, 2024). "High levels of C-reactive protein (≥ 0.2 mg/dL) and vitamin D deficiency are also reported in individuals with cardiovascular diseases." (PMID 38243935, 2024). "Calculation and intergroup comparisons of SCORE 2019 risk scores demonstrated that the calculated 10-year risk for fatal cardiovascular disease was significantly higher in the CRP+ SSc group relative to the CRP− SSc group (p = 0.040)." (PMID 39564499, 2024). "The SMART study found that higher levels of IL-6, CRP, and D-dimer are associated with an increased risk of cardiovascular diseases in PWH, as an independent factor." (PMID 39456715, 2024). "Elevated levels of CRP, as one of the inflammation biomarkers, were significantly associated with increased risk of cardiovascular disease occurrence and mortality." (PMID 38699426, 2024). "Risk factors of cardiovascular disease, comorbidity and C reactive protein (CRP) serum also showed a high degree of variability among the groups." (PMID 39644770, 2024). "Only the changes from baseline in hs‐CRP, a marker for cardiovascular disease (CVD) risk or acute inflammation, were mildly, but significantly, decreased in the MS‐20 group when compared to the placebo group." (PMID 38628176, 2024).
cardiovascular disease (continued). "Those with a CRP level considered at higher risk of cardiovascular disease, ≥ 3μg/ml, had reduced CRP after the treatment period." (PMID 38528176, 2024). "One rising area of interest is the incorporation of low concentrations of CRP, so called high-sensitive (hs-) CRP, in the risk assessment and treatment monitoring of cardiovascular diseases (CVDs)." (PMID 39176390, 2024). "Since a high level of CRP has been associated with an increased risk of cardiovascular disease and mortality in frail older adults, decreasing CRP levels is particularly important." (PMID 39518709, 2024). "Elevated CRP levels have also been associated with hyperactivity of the endothelin-1 (ET-1) system, which is linked with cardiovascular disease development and progression." (PMID 39301363, 2024). "In the case of need, it is also possible to measure the level of the hs-CRP (high-sensitivity CRP) that is more specific and is used as a diagnostic tool to assess cardiovascular disease risk." (PMID 39199534, 2024). "CRP is not only an inflammatory marker, but also a predictor and risk factor for cardiovascular disease." (PMID 38532316, 2024). "The current systematic review and meta-analysis aims to understand and explore the levels of high-sensitivity C-reactive protein (hs-CRP) and other cardiovascular disease (CVD)-risk factors including lipid profiles among PLWH on HAART." (PMID 38308222, 2024). "Several studies also suggest that CRP is an indicator of subclinical cardiovascular events in patients with RA and higher CRP levels are associated with a greater risk of cardiovascular disease in this group." (PMID 39281435, 2024). "The GlycA signal from NMR represents the integrated concentration and glycosylation of several acute phase proteins and is a novel marker of systemic inflammation, suggested to be a better predictor of cardiovascular disease (CVD) risk than CRP." (PMID 39106867, 2024). "We now know that previously reported associations between CRP and cardiovascular disease were likely driven by IL-6 signalling." (PMID 38951047, 2024). "C-reactive protein (CRP) has been demonstrated to be a risk factor not only for cardiovascular disease but also for CKD." (PMID 38612488, 2024). "CRP has recently been investigated as a research marker of cardiovascular diseases, and recent studies have reported that increased CRP levels are associated with DM." (PMID 39408723, 2024). "It has been shown that there is a longitudinal association of elevated CRP with systemic inflammation and cardiovascular disease risk." (PMID 39215289, 2024). "The increase of C-reactive protein correlate with the risk of getting coronary artery disease (CAD) or cardiovascular disease (CVD)." (PMID 38291355, 2024). "The liver also produces C-reactive protein (CRP), an inflammation marker and cardiovascular disease risk factor." (PMID 38525188, 2024). "Its evaluation in cardiovascular disease appears to be associated with altered CRP and increased cardiovascular risk." (PMID 38398769, 2024). "Background and aims: Elevated high-sensitivity C-reactive protein (hs-CRP) levels are associated with an increased risk of cardiovascular disease, indicating systemic inflammation." (PMID 39301363, 2024). "A serological marker of systemic inflammation known as C-reactive protein has been linked to an increased risk for a number of pathological conditions, including cardiovascular diseases." (PMID 38077410, 2023). "More than 30% of patients had hs-CRP levels higher than 3.0 mg/L, representative of a high risk of cardiovascular disease." (PMID 37770999, 2023). "Previous evidence on the association between C-reactive protein (CRP) and cardiovascular disease (CVD) remains ambiguous." (PMID 37298077, 2023). "For instance, a precise and quantitative risk assessment for cardiovascular disease is provided by a high-sensitivity C-reactive protein test." (PMID 36832152, 2023).